LINC00628 (long independently transcribed non-coding RNA 628)
Gene: Long non-coding RNA gene on chromosome 1 (204,368,431 to 204,369,719, reverse strand). Ensembl gene ENSG00000280924.
Diseases named in the same sentence as LINC00628 in open-access papers:
LINC00628 is named in the same sentence as 8 diseases in open-access papers, as found by Europe PMC text mining. Sharing a sentence is not in itself a finding about the gene and the disease. The quoted sentences say what the papers report.
breast carcinoma (2 papers, 2021). "Furthermore, since the aberrantexpression of this lincRNA was significantly linked to theER expression, physical activity, diabetes disease, stress,age at menopause and obesity in breast cancer patients,LINC00628 expression can be proposed as a biomarker inpatients with breast cancer." (PMID 34455716, 2021).
osteosarcoma (2 papers, 2021 to 2022). A usually aggressive malignant bone-forming mesenchymal neoplasm, predominantly affecting adolescents and young adults. "For example, overexpression of LINC00628 inhibited the proliferation and migration of osteosarcoma cells, whereas its knockdown in gastric cells had a similar inhibitory effect." (PMID 35592248, 2022).
tumor (4 papers, 2016 to 2022). "Reduced LINC00628 expression is associated with increased tumor burden." (PMID 27272474, 2016). "Meanwhile, up-regulated LINC00628 contributes to decreased tumor burden." (PMID 27272474, 2016). "So these results may explain why LINC00628 functions as a tumor suppressor." (PMID 27272474, 2016). "Thus, LINC00628 likely functions as an oncogene in LUAD and promotes tumor cell migration and invasion." (PMID 35592248, 2022).
cancer (3 papers, 2016 to 2022). A tumor composed of atypical neoplastic, often pleomorphic cells that invade other tissues. "We confirmed that LINC00628 functions as a GC suppressor through suppressing proliferation, migration and colony formation of cancer cells." (PMID 27272474, 2016). "However, studies show that LINC00628 can function as an oncogene or tumor suppressor in different cancers." (PMID 35592248, 2022).
LINC00628 also shares sentences with these, for which no sentence is quoted: gastric cancer (1 paper); hepatocellular carcinoma (1); lung adenocarcinoma (1); Obesity (1).